FOXO1 (forkhead box O1)
Diseases named in the same sentence as FOXO1 in open-access papers (continued):
Sharing a sentence is not in itself a finding about the gene and the disease.
laryngeal squamous cell carcinoma (2 papers, 2021 to 2025). A squamous cell carcinoma that arises from the larynx. "MiR-26a is increased and FOXO1 is reduced in human laryngeal squamous cell carcinoma, Sevoflurane inhibits proliferation and mediates apoptosis of LSCC cells." (PMID 34511023, 2021). "This investigation aimed at determining the expression of MiR-26a and FOXO1 in human laryngeal squamous cell carcinoma, elucidating the effects of Sevoflurane in proliferation and apoptosis of LSCC cells." (PMID 34511023, 2021). "The use of Sevoflurane to target miR-26a/FOXO1 may be a novel and effective alternative for laryngeal squamous cell carcinoma therapy." (PMID 34511023, 2021).
lymphedema (2 papers, 2022 to 2024). Excess fluid collection in tissues, causing swelling. "Therefore, in addition to Foxo1 deletion, moderately increased β-catenin activity can rescue the valve loss in Foxc2 heterozygous mice, the mouse model for lymphedema-distichiasis." (PMID 36742198, 2022). "Hence, drug-induced inhibition of Foxo1 can be clinically relevant in the treatment of lymphedema caused by valve defects." (PMID 36742198, 2022). "Moreover, Foxo1 ablation in Foxc2 heterozygous mice, the model of human lymphedema-distichiasis disease, rescues both the valve loss and valve dysfunction to the wildtype level." (PMID 36742198, 2022). "The transcription factor FOXO1 represses lymphatic valve formation by inhibiting the expression of these genes, which makes FOXO1 a potential target for treating lymphedema." (PMID 36742198, 2022). "It was the first study to show that valve defects in congenital lymphedema can be restored after the impaired lymphatic vasculature has formed, which drove us to further investigate the function of FOXO1 inhibition in treating lymphedema." (PMID 36742198, 2022). "More importantly, ablation of Foxo1 in a mouse model for human disease lymphedema–distichiasis, the Foxc2 heterozygous mice, completely resolves both the loss of valves and the leakiness of valves in this disease model." (PMID 36742198, 2022). "Therefore, in addition to genetic deletion of Foxo1, valve defects in a primary lymphedema mouse model can also be rescued by using a drug to pharmacologically inhibit FOXO1." (PMID 36742198, 2022).
lymphocytic leukemia (2 papers, 2012 to 2020). "We examined this concept using available data on lymphoid leukemia patients to examine the effect of predicted associations with cooperative binding of FOXO1 and ETV6 (DOID:0050745, k-mer GAAAACCGAANM; mean k-mers Z-score = 3.2)." (PMID 31913281, 2020). "Together with reports of FOXO1 and ETV6 as putative tumor suppressors in lymphomas this suggests an important role of this TF pair in lymphoid leukemia." (PMID 31913281, 2020).
malnutrition (2 papers, 2022 to 2025). Inadequate nutrition resulting from poor diet, malabsorption, or abnormal nutrient distribution. "To further explore the effects of FoxO1MPOA on metabolic adaptation to nutritional deficiency, we fasted female FoxO1-KOMPOA mice for 18 hours overnight, followed by a refeeding phase, and monitored their metabolic changes using the Sable Promethion system." (PMID 40667056, 2025). "It has been observed that the expression of forkhead box protein O1 (FOXO1), one of the transcription factors, is increased in some conditions such as malnutrition, inactivity, and cancer." (PMID 35340314, 2022).
mantle cell lymphoma (2 papers, 2022 to 2025). Mantle cell lymphoma is a rare form of malignant non-Hodgkin lymphoma affecting B lymphocytes in the lymph nodes in a region called the ``mantle zone''. "Through screening for molecular vulnerabilities of mantle cell lymphoma (MCL), we identified a set of transcription factors (TFs) including FOXO1, EBF1, PAX5, and IRF4 that are essential for MCL propagation." (PMID 36282572, 2022).
myelodysplastic syndrome (2 papers, 2020 to 2022). A clonal hematopoietic disorder characterized by dysplasia and ineffective hematopoiesis in one or more of the hematopoietic cell lines. "Little is known about the function of tumor suppressor gene FOXO1 in myelodysplastic syndromes (MDS)." (PMID 33584800, 2020).
myeloid leukemia (2 papers, 2016 to 2022). A clonal proliferation of myeloid cells and their precursors in the bone marrow, peripheral blood, and spleen. "We further show that FOXO1, but not its close paralog FOXO3, can reprogram myeloid leukemia cells and induce B-lineage gene expression." (PMID 36282572, 2022).
Nephroblastoma (2 papers, 2013). An embryonal neoplasm characterized by the presence of epithelial, mesenchymal, and blastema components. "Our genomic analysis led to the identification of nephroblastoma overexpressed gene (Nov, also known as Ccn3) as a novel FoxO1 target." (PMID 23705021, 2013). "In the present study, we identify for the first time Nephroblastoma overexpressed gene (Nov/Ccn3) as a novel transcriptional target of FoxO1 in β-cells." (PMID 23705021, 2013).
non-Hodgkin lymphoma (2 papers, 2022). Distinct from Hodgkin lymphoma both morphologically and biologically, non-Hodgkin lymphoma (NHL) is characterized by the absence of Reed-Sternberg cells, can occur at any age, and usually presents as a localized or generalized lymphadenopathy associated with fever and weight loss. "Together, our results revealed the existence of FOXO1 loss-of-function mutations in non-Hodgkin lymphoma, suggesting that FOXO1 plays a complex role in this disease." (PMID 35079069, 2022). "However, other researchers found that FOXO1 promoted resistance of non-Hodgkin lymphomas to anti-CD20-based therapy and played a tumor-promoting role in FLT3-ITD+ AML through a complex mechanism, respectively." (PMID 36290822, 2022).
osteonecrosis (2 papers, 2022). A none disease characterized by death of bone tissue due to a lack of blood supply. "We explored the role of PI3K/AKT/FOXO1 signaling pathway and its downstream targets during glucocorticoid -induced osteonecrosis of the femoral head." (PMID 35529482, 2022). "Our research offers new insights into the underlying molecular mechanisms of glucocorticoid-induced osteonecrosis in SONFH and proposes FOXO1 as a therapeutic target for this disease." (PMID 35529482, 2022).
pancreatitis (2 papers, 2021 to 2022). Inflammation of the pancreas. "Our research showed that EV miR-183-5p derived from ACs may induce M1 macrophage polarization by inhibiting FoxO1, thus aggravating pancreatitis." (PMID 35911777, 2022).
pituitary adenomas (2 papers, 2022 to 2025). "A similar mechanism was also observed in prolactin pituitary adenomas where FOXO1 suppresses the promoter of PRL gene." (PMID 35270010, 2022).
SAPHO syndrome (2 papers, 2019 to 2021). SAPHO syndrome (acronym for Synovitis, Acne, Pustulosis, Hyperostosis and Osteitis) is an auto-inflammatory disease, mainly characterized by the association of neutrophilic cutaneous involvement and chronic osteomyelitis. "The etiopathogenetic mechanism of SAPHO syndrome, although having been proposed involving bacteriologic, immunologic and genetic factors such as autophagy, interleukin-1(IL-1), Forkhead Box O1(FoxO1) and propionibacterium (Cutibacterium) acnes, remains poorly understood." (PMID 30654792, 2019).
schizophrenia (2 papers, 2024). A major psychotic disorder characterized by abnormalities in the perception or expression of reality. "FOXO1, involved in oxidative stress response and apoptosis, may be upregulated as a protective mechanism against cellular stress commonly observed in schizophrenia." (PMID 39061390, 2024).
serous ovarian cancer (2 papers, 2022 to 2023). "In serous ovarian cancer cells, overexpressed HDAC9 can activate EMT and promote cell migration and invasion via increasing the nuclear localization of forkhead box O1 (FOXO1) and promoting the expression of the transforming growth factor β (TGFβ)." (PMID 37894746, 2023). "In serous ovarian cancer, overexpressed HDAC9 can increase the nuclear localization of FOXO1 and promote the expression of TGF-β." (PMID 35203583, 2022). "Our findings suggested that, in serous ovarian cancer, overexpressed HDAC9 may activate epithelial–mesenchymal transition (EMT) by increasing the nuclear accumulation of FOXO1." (PMID 35203583, 2022). "Our data suggest that FOXO1 inhibitors and TGF-β inhibitors may enhance the therapeutic effect of HDAC9 inhibitors on serous ovarian cancer." (PMID 35203583, 2022). "In serous ovarian cancer, HDAC9 may promote cell migration by increasing the nuclear accumulation of FOXO1 and promoting TGF-β expression." (PMID 35203583, 2022). "In serous ovarian cancer, overexpressed HDAC9 may promote cell migration through the forkhead box protein O1 (FOXO1)/transforming growth factor-beta (TGF-β) axis." (PMID 35203583, 2022).
skeletal muscle cancer (2 papers, 2012 to 2020). A malignant neoplasm arising from skeletal muscle. "Notably, in contrast to the previous study on human skeletal muscle cancer cachexia, we observed a more than 5-fold upregulation of FOXO1, a key regulator of gene expression during skeletal muscle atrophy (p<0.05)." (PMID 22721276, 2012).
solitary fibrous tumor (2 papers, 2018 to 2025). Solitary fibrous tumor (SFT) represents a diverse group of ubiquitous rare spindle cell neoplasms that may be benign or malignant and that most frequently arises from the pleura and peritoneum and rarely from other sites such as head and neck, liver and skeletal muscle. "We hypothesized that SCLs, CAFs and MFBs would share common molecular signatures involving FOXO1, ROS and p38 MAPK and that their expression patterns were different from those tumors without monoallelic 13q14 deletion such as solitary fibrous tumors (SFTs)." (PMID 28887603, 2018).
spinal muscular atrophy (2 papers, 2022 to 2024). A motor neuron disease that affect the muscles, and characterized by muscle weakness and atrophy resulting from progressive degeneration and irreversible loss of the anterior horn cells in the spinal cord (i.e., lower motor neurons) and the brain stem nuclei. "Inhibition of FOXO1 not only mitigated myogenic and metabolic abnormalities in ALS myoblast cells but also in other two MN disorders with muscle involvement, such as Spinal Muscular Atrophy (SMA) or Spinal Bulbar Muscular Atrophy (SBMA)." (PMID 39283487, 2024).
Splenomegaly (2 papers, 2021 to 2023). Abnormal increased size of the spleen. "The study using mice with T cell-specific deletion of Foxo1 and Foxo3 alleles found that Foxo1−/−Foxo3−/− mice developed splenomegaly and lymphadenopathy at 8 weeks of age." (PMID 33748292, 2021).
subarachnoid hemorrhage (2 papers, 2021 to 2025). A serious neurological disorder characterized by intracranial hemorrhage into the subarachnoid space. "Foxo1 may be involved in OGD/R-induced injury in BMECs and may play a role in early brain injury after subarachnoid hemorrhage." (PMID 40002863, 2025).
tongue cancer (2 papers, 2015 to 2022). A malignant neoplasm affecting the tongue. "Bioinformatics analysis combined with ChIP-qPCR uncovered the physical binding of FOXO1 to the miR-491-3p promoter in tongue cancer cells." (PMID 25749387, 2015). "We also found the level of p-FOXO1 increased in tongue cancer cell lines and clinical samples with high Rictor and mTORC2 activity and low expression levels of miR-491-3p." (PMID 25749387, 2015). "Both Rictor knockdown and mTOR inhibitor inactivated the mTORC2 downstream signaling such as Akt, SGK and FOXO1, and re-sensitized tongue cancer cells to chemotherapy." (PMID 25749387, 2015). "We performed in situ hybridizations (ISH) to detect miR-491-3p and immunohistochemical staining to examine Rictor, p-Akt(Ser473), p-SGK1(Ser422) and p-FOXO1(Thr24) in the tissues from 84 tongue cancer patients who received chemotherapy based on PYM and/or cDDP." (PMID 25749387, 2015). "To validate the direct association of FOXO1 with the promoter of miR-491-3p, we performed ChIP-qPCR assays and discovered that FOXO1 most significantly bound to site A and site D. The bindings in Tca8113/PYM cells were much lower than those in the chemo-sensitive tongue cancer cell lines." (PMID 25749387, 2015).
tongue squamous cell carcinoma (2 papers, 2017 to 2025). A squamous cell carcinoma that arises from the tongue. "Knockdown of miR-21-5p significantly reduced the expression levels of PI3K, AKT, and p-FOXO1 and stimulated apoptosis of Cal27 and SCC9 cells, suggesting that inactivation of PI3K/AKT/FOXO1 signaling is an effective therapeutic strategy for tongue squamous cell carcinoma (TSCC)." (PMID 40746882, 2025). "Reduced expression of both FOXO1 and HBP1 was also found in two tongue squamous cell carcinoma datasets in the Oncomine database." (PMID 28099936, 2017).
tuberculosis (2 papers, 2013 to 2021). A chronic, recurrent infection caused by the bacterium Mycobacterium tuberculosis. "An interesting observation pertained to candidate hsa-miR-582-5p, which was found to be upregulated in monocytes from patients with active tuberculosis, resulting in monocyte apoptosis inhibition through the targeting of forkhead box protein O1 (FOXO1)." (PMID 35008531, 2021).
ulcers (2 papers, 2024 to 2025). "Similarly, this study demonstrated that the levels of SIRT-1, PGC-1α, and FOXO1 were decreased in response to ethanol-induced ulcers." (PMID 40867886, 2025). "Likewise, this study found that gene expression of Sirt-1, PGC-1α, and HO-1 had been downregulated while FOXO1 expression was upregulated as a response to ethanol-induced ulcers." (PMID 39314751, 2024).
urothelial carcinoma (2 papers, 2022). A malignant neoplasm derived from the transitional epithelium of the urinary tract (urinary bladder, ureter, urethra, or renal pelvis). "However, for urothelial carcinoma, FOXO1 amplification indicates poor prognosis." (PMID 35609322, 2022). "In addition, in urothelial carcinoma (UTUC), FOXO1 overexpression indicates worse outcomes due to its roles in accelerating growth and metastasis of tumor cells." (PMID 35800988, 2022).
vitiligo (2 papers, 2020 to 2022). Generalized well circumscribed patches of leukoderma that are generally distributed over symmetric body locations and is due to autoimmune destruction of melanocytes. "Another study reported the downregulation of FOXO1 in vitiligo lesional skin." (PMID 35406685, 2022). "IGFBP5, FOXO1, and WIF1 downregulation may indicate a loss of tolerance mechanisms or melanocyte regenerative capacity in the skin in canine VKH and vitiligo." (PMID 33384688, 2020).
abdominal aortic aneurysm (1 paper, 2021). Enlargement and ballooning of the vessel that supplies arterial blood to the abdomen, pelvis and legs. "In addition, we also found that FoxO1 was upregulated in abdominal aortic aneurysm tissues, however, this study only focused on FoxO3, the role of FoxO1 in AAA needs to be further explored in the future." (PMID 33828087, 2021).
AIDS (1 paper, 2023). A syndrome resulting from the acquired deficiency of cellular immunity caused by the human immunodeficiency virus (HIV). "The hsa-miR-185-3p modulating transcription factor Foxo1 plays a foremost role in AIDs and can serve as a diagnostic marker of SLE." (PMID 37313407, 2023).
airway allergy (1 paper, 2021). "Moreover, the transcription factor FOXO1, which was recently described to be essential for Th9 cell differentiation and IL-9 production, was clearly reduced upon Tgfbr2 ablation, correlating with reduced airway allergy." (PMID 35069535, 2021).
allergic disease (1 paper, 2016). An immune response that occurs following re-exposure to an innocuous antigen, and that requires the presence of existing antibodies against that antigen. "The present finding that FoxO1 as a central effector molecule in the development of allergic inflammation suggests a new therapeutic approach to alleviate the suffering of TH2/M2 cell-related allergic diseases." (PMID 27007158, 2016). "Perhaps most importantly, our data shows an important role for FoxO1 in macrophages in the contribution of allergic disease, and highlight the separate role that FoxO1 could be a major inducer of IRF4 in macrophages, through gain and loss-of-function studies." (PMID 27007158, 2016).
American trypanosomiasis (1 paper, 2022). A parasitic infection caused by Trypanosoma cruzi. "CircRNA_400090 could regulate the expression of FOXO1, CCND2 and SMAD2 to participate the pathways of hsa04068: FoxO signalling pathway or hsa05142: Chagas disease (American trypanosomiasis)." (PMID 35840955, 2022).
Anorexia (1 paper, 2020). Lack of desire to eat (loss of appetite). "Glucose administration likely stimulated the insulin receptor-AKT signaling pathway to decrease FOXO1 activation to blunt the increase in PDK4 levels resulting from anorexia to maintain energy generation." (PMID 33014275, 2020). "However, the infection led to severe anorexia, which also increases PDK4 levels in some tissues such as those in the muscle and liver due to increased FOXO1, PPAR-α, and glucocorticoid receptor (GR) transcriptional activity." (PMID 33014275, 2020). "Therefore, FOXO1 hyperactivation may be a pathological event in mouse IAV infection as it is induced by both increased ROS levels and the anorexia that occurs following IAV infection." (PMID 33014275, 2020).
anorexia nervosa (1 paper, 2025). A disorder most often seen in adolescent females characterized by a refusal to maintain a minimally normal body weight, an intense fear of gaining weight, a disturbance in body image, and, in postmenarcheal females, the development of amenorrhea. "SIRT1 activation by resveratrol reduced BMA and promoted osteogenesis in an anorexia nervosa model by modulating the acetylation levels of Runx2 and FoxO1." (PMID 40243497, 2025).
Apert syndrome (1 paper, 2022). Apert syndrome (AS) is a frequent form of acrocephalosyndactyly, a group of inherited congenital malformation disorders, characterized by craniosynostosis, midface hypoplasia, and finger and toe anomalies and/or syndactyly. "Interestingly, in Apert syndrome, an upregulation of PI3L/Akt can be observed which results in decreased FOXO1." (PMID 35455561, 2022).
Arterial thrombosis (1 paper, 2019). The formation of a blood clot inside an artery. "Taken together, our data suggest that by enhancing autophagy flux and decreasing the release of vWF and P-selectin, the Sirt1/FoxO1 pathway may be a promising target to prevent AS and arterial thrombosis." (PMID 31450612, 2019). "Sirt1/FoxO1 may be a potential target to prevent the development of AS and arterial thrombosis." (PMID 31450612, 2019).